NTHL1 (nth like DNA glycosylase 1)
Description:
Bifunctional DNA N-glycosylase with associated apurinic/apyrimidinic (AP) lyase function that catalyzes the first step in base excision repair (BER), the primary repair pathway for the repair of oxidative DNA damage. The DNA N-glycosylase activity releases the damaged DNA base from DNA by cleaving the N-glycosidic bond, leaving an AP site. The AP-lyase activity cleaves the phosphodiester bond 3' to the AP site by a beta-elimination. Primarily recognizes and repairs oxidative base damage of pyrimidines. Also has 8-oxo-7,8-dihydroguanine (8-oxoG) DNA glycosylase activity. Acts preferentially on DNA damage opposite guanine residues in DNA. Is able to process lesions in nucleosomes without requiring or inducing nucleosome disruption.
Synonyms: hNTH1; NTH1; OCTS3; FAP3
Tractability: Small molecule: a structure with a bound ligand is known; a high-quality ligand is known. PROTAC: UniProt records ubiquitination sites on it; ubiquitination databases record sites on it; its protein half-life has been measured.
Target class: Enzyme; Hydrolase
Gene: Protein-coding gene on chromosome 16 (2,039,814 to 2,047,866, reverse strand). Ensembl gene ENSG00000065057.
Subcellular location: Nucleus; Mitochondrion
Pathways (Reactome):
DNA Repair: Cleavage of the damaged pyrimidine; Displacement of DNA glycosylase by APEX1; Recognition and association of DNA glycosylase with site containing an affected pyrimidine
Disease: Defective NTHL1 substrate binding; Defective NTHL1 substrate processing
Gene Ontology:
Molecular function: class I DNA-(apurinic or apyrimidinic site) endonuclease activity; damaged DNA binding; DNA N-glycosylase activity; DNA-(apurinic or apyrimidinic site) endonuclease activity; double-stranded DNA binding; protein binding; endonuclease activity; oxidized purine nucleobase lesion DNA N-glycosylase activity; oxidized pyrimidine nucleobase lesion DNA N-glycosylase activity; 4 iron, 4 sulfur cluster binding; catalytic activity; DNA binding
Biological process: base-excision repair, AP site formation; nucleotide-excision repair; depyrimidination; base-excision repair; DNA repair
Cellular component: mitochondrion; nucleus; nucleoplasm
Genetic constraint (gnomAD): Loss-of-function variants: 32 observed, 31.11 expected, observed/expected ratio (o/e) 1.03, 90% interval 0.77 to 1.38. The upper end of that interval is the gene's LOEUF score, 1.38, which puts it in group 5 of 6, group 1 being the genes least tolerant of losing a copy. Missense variants: 501 observed, 407.22 expected, observed/expected ratio (o/e) 1.23, 90% interval 1.14 to 1.33. Synonymous variants: 188 observed, 174.11 expected, observed/expected ratio (o/e) 1.08, 90% interval 0.96 to 1.22.
Gene-disease validity (ClinGen):
ClinGen rates the evidence that NTHL1 causes each of these diseases.
NTHL1-deficiency tumor predisposition syndrome (autosomal recessive): Definitive. Biallelic constitutional/germline loss-of-function NTHL1 variants confer predisposition to tumor formation demonstrating ‘COSMIC Signature 30’ mutation profile.
Homologues: Orthologues: chimpanzee NTHL1 (99% identical), macaque NTHL1 (85% identical), pig NTHL1 (82% identical), dog NTHL1 (79% identical), mouse Nthl1 (79% identical), rat Nthl1 (78% identical), guinea pig NTHL1 (71% identical), zebrafish nthl1 (58% identical), tropical clawed frog nthl1 (56% identical), Drosophila melanogaster Nthl1 (44% identical), Caenorhabditis elegans nth-1 (37% identical). Paralogues in human: MUTYH (19% identical).
Diseases named in the same sentence as NTHL1 in open-access papers:
NTHL1 is named in the same sentence as 72 diseases in open-access papers, as found by Europe PMC text mining. Sharing a sentence is not in itself a finding about the gene and the disease. The quoted sentences say what the papers report.
polyposis (29 papers, 2016 to 2026). "In order to establish if the NTHL1 p.Q82* mutation in exon 2 is associated with cancer development or influences the disease course in polyposis patients, we genotyped the gathered DNA samples using HRM analysis followed by Sanger sequencing." (PMID 37834005, 2023). "RAD18 Arg302Gln increases the colon cancer risk in Japanese patients, while biallelic mutations in NTHL1, result in NTHL1-associated polyposis." (PMID 37738679, 2023). "The disease associated with biallelic NTHL1 deleterious variants was initially named NTHL1-associated polyposis, but later the name NTHL1 tumor syndrome was proposed to accommodate for the increased risk for several cancers." (PMID 37727376, 2023). "In our group of pathogenic NTHL1 biallelic variant carriers, it is evident that, as described in the literature, polyposis, CRC and BC are the main phenotype characteristics of this syndrome." (PMID 37727376, 2023). "In the analyzed study group, NTHL1 p.Q82* allele T carriers were identified in 0.47% of cases with evidence of hereditary predisposition to polyposis and in 0.32% of the control group." (PMID 37834005, 2023). "Although inactivation of the NTHL1 gene was initially described as being associated with polyposis and CRC, the spectrum of neoplasms presented by the families is widening." (PMID 37727376, 2023). "This has also been reported by other authors, emphasizing that the presence of polyposis remains the main characteristic associated with biallelic NTHL1 variant carriers." (PMID 37727376, 2023). "Recently, biallelic germline variants of the DNA glycosylase genes MUTYH and NTHL1 were linked to polyposis susceptibility." (PMID 36387175, 2022). "Development of NTHL1-associated polyposis is caused by biallelic PVs in NTHL1 and the inheritance pattern is autosomal recessive." (PMID 34620187, 2021). "At first, p.Gln90 nonsense mutation was detected in the NTHL1 gene, and then the other eight different pathogenic variants, all of which are nonsense or frameshift mutations, have been detected in patients with NTHL1-associated polyposis." (PMID 32258104, 2020). "This family further expands the phenotypic spectrum linked to NTHL1-associated polyposis and raises the total number of families to 19 (32 individuals)." (PMID 31645984, 2019). "To date, two autosomal recessive polyposis syndromes have been identified, MUTYH-associated polyposis and NTHL1-associated polyposis." (PMID 27060000, 2016). "Moreover, biallelic NTHL1 (OMIM# 616415) variants have been associated with polyposis and multi-organ cancer predisposition." (PMID 36387175, 2022). "Previously called NTHL1-associated polyposis, today, the preferred name for this syndrome is NTHL1 Tumor Syndrome, based on the high risk to different benign and malignant tumor types that biallelic variants in NTHL1 confer." (PMID 33806975, 2021). "As of January 2020, reports of 34 patients with NTHL1-associated polyposis have been published." (PMID 34620187, 2021). "Thus far, two autosomal recessive Mendelian CRC syndromes have been described, namely MUTYH-associated polyposis (MAP) caused by biallelic mutations in the MUTYH gene and NTHL1-associated polyposis caused by biallelic mutations in the NTHL1 gene." (PMID 28445943, 2017). "In both MUTYH- as well as NTHL1-associated polyposis, the base excision repair pathway is affected." (PMID 27060000, 2016). "Therefore, it is plausible that POLE and NTHL1 co-occurring truncating variants may have a synergistic effect leading to a polyposis predisposition in high division tissues such as the colon epithelium." (PMID 31285513, 2019). "Biallelic loss of NTHL1 or MUTYH results in NTHL1-associated polyposis (NAP) and MUTYH-associated polyposis (MAP), respectively." (PMID 41595502, 2026). "We examined 644 polyposis probands and 634 control subjects from the Polish population for the presence of p.Q82* in the NTHL1 gene." (PMID 37834005, 2023).
polyposis (continued). "All these facts make the p.Q82* of the NTHL1 gene screening reasonable in polyposis patients (especially in an unusual disease course), with APC, MUTYH, STK11, BMPR1A, and SMAD4 mutations excluded." (PMID 37834005, 2023). "All index patients with personal/family history of polyposis and/or multi-tumor phenotype should ideally be studied using a NGS panel of cancer predisposition genes that includes NTHL1." (PMID 37727376, 2023). "The most recently identified polyposis syndromes are NTHL1-associated polyposis and MSH3-associated polyposis." (PMID 33922305, 2021). "Similar to the NTHL1- and MUTYH-deficiency syndromes, which are associated with CRC and polyposis, the MCM9-deficiency syndrome observed in our population-based analysis and case series may warrant comparable surveillance protocols." (PMID 40684266, 2025). "Moreover, we found no discernible SBS88 signature that is linked to colibactin and was reported to occur in colorectal tumors from NTHL1- and MUTYH-associated polyposis patients." (PMID 38725616, 2024). "Seven NTHL1 biallelic variant carriers were identified in index patients with polyposis and no biallelic NTHL1 variants were identified in patients with familial/personal history of multiple tumors." (PMID 37727376, 2023). "Our findings further indicate that the NTHL1 tumor syndrome is a multi-tumor syndrome strongly associated with polyposis and not with multiple tumors without polyposis." (PMID 37727376, 2023). "Our findings indicate that the NTHL1 tumor syndrome is a multi-tumor syndrome strongly associated with polyposis and not with multiple tumors without polyposis." (PMID 37727376, 2023). "In patients with polyposis who do not have a mutation that causes polyposis, screening for the NTHL1 gene in the p.Q82* variant should be recommended, but in the case of an atypical course of FAP, APAP, or hamartomatous and serrated polyposis syndromes only." (PMID 37834005, 2023). "In addition to BC, the risk associated with monoallelic NTHL1 variants has previously been investigated in CRC, polyposis, and in a pan-cancer patient population." (PMID 38036545, 2023). "NTHL1 heterozygotes do not appear to be at clinically significant increased risk for polyposis and/or CRC and BC, but a slightly increased risk cannot be excluded, as has been described for patients with heterozygous variants in the MUTYH gene." (PMID 37727376, 2023). "The prevalence of NTHL1 biallelic germline carriers is rare and has been estimated to be around 1:114,770, five times lower than the estimated prevalence for MUTYH-associated polyposis (1:19,079)." (PMID 33806975, 2021). "Here, we show that monoallelic LoF variants in NTHL1 are not enriched in individuals with polyposis and/or CRC compared to the general population." (PMID 32860789, 2020). "NTHL1, a novel recessive polyposis and CRC-predisposing gene, is the second DNA glycosylase gene of the BER pathway with a high-penetrant predisposition to develop polyposis." (PMID 32258104, 2020). "However, because we identified NTHL1 LoF variants in individuals with polyposis or CRC, we do not consider a major difference between these 2 phenotypes." (PMID 32860789, 2020). "In this study, no NTHL1 heterozygous carriers that underwent colonoscopy were identified with polyposis (≥ 10 polyps)." (PMID 40237887, 2025). "We identified no pathogenic variants in more recently discovered polyposis predisposition genes (POLE, POLD1 or NTHL1), rendering the presence of such founder variants rare." (PMID 39516274, 2024). "Three NTHL1 tumor syndrome families were identified in the group of patients with polyposis and none in patients with familial/personal history of multiple tumors." (PMID 37727376, 2023). "In addition to polyposis, CRC and BC, we found uterine lesions, basal cell carcinoma and pancreatic cancer in our NTHL1 tumor syndrome families." (PMID 37727376, 2023).
polyposis (continued). "Likewise, analysis of 5,942 individuals with unexplained polyposis or familial CRC found no enrichment of monoallelic NTHL1 PVs when compared to the general population." (PMID 40237887, 2025).
colorectal cancer (23 papers, 2006 to 2025). A primary or metastatic malignant neoplasm that affects the colon or rectum. "Colorectal cancers (CRCs) from people with biallelic germline likely pathogenic/pathogenic variants in MUTYH or NTHL1 exhibit specific single base substitution (SBS) mutational signatures, namely combined SBS18 and SBS36 (SBS18+SBS36), and SBS30, respectively." (PMID 39793275, 2025). "Subsequently, since NTHL1 mutations can cause a wide variety of cancers in addition to colorectal cancer, the designation “NTHL1 syndrome” was proposed." (PMID 34026625, 2021). "One example is the NTHL1 variant in an individual with meningioma and colorectal cancer in the Whitworth study." (PMID 34711244, 2021). "Fourteen breast cancers and ovarian cancer from individuals with heterozygous NTHL1 germline variants, together with breast cancer and colorectal cancer from the individual homozygous for germline LoF variants, were sequenced." (PMID 33980861, 2021). "Rare protein truncating variants of NTHL1 gene are causative for the recently described, recessively inherited NTHL1 tumor syndrome that is characterized by an increased lifetime risk for colorectal cancer, colorectal polyposis, and breast cancer." (PMID 32949222, 2020). "Similarly, deficiency in the Nth like DNA glycosylase 1 (NTHL1) is associated with a tumor syndrome that is dominated by colorectal cancer but includes several other malignancies." (PMID 35935942, 2022). "NTHL1 tumor syndrome, also known in the literature as NTHL1-associated polyposis, is a multi-tumor spectrum disease, whose narrow spectrum is mostly characterized by an increased lifetime risk for colorectal polyposis, colorectal cancer (CRC), and breast cancer (BC)." (PMID 37727376, 2023). "The studies from NTHL1 families add evidence for this: the same causative gene defect(s) in either recessive or dominant mode of inheritance, depending on the colorectal cancer/polyposis syndrome in concern, can also lead to predisposition to cancer in various different tissues." (PMID 32949222, 2020). "Recently, numerous findings highlighted the importance of detectable variation in NTHL1 and its consequences in colorectal cancer among many ethnic groups." (PMID 37298600, 2023). "Recent reports have indicated biallelic mutations in the NTHL1 gene, which is involved in base excision repair (BER), as predisposing to an elevated risk of colorectal cancer (CRC)." (PMID 37834005, 2023). "Up to the date of reporting, 20 of the 36 NTHL1 biallelic carriers (56%) were diagnosed with colorectal cancer, eight of whom diagnosed before the age of 50 years, and the median age at first CRC diagnosis was 53 years (age range: 33–73 years)." (PMID 33806975, 2021). "The absence of homozygotes can also be explained by sample size of the current cohorts, but nevertheless NTHL1 p.Q90* homozygosity appears to be an extremely rare event in cases unselected for the family history of adenomatous polyposis and colorectal cancer." (PMID 32949222, 2020). "Other rare inherited variants have been reported in NTHL1 and MUTYH with strong associations to colorectal cancer." (PMID 26519467, 2015). "Our data reflects the recent findings that heterozygous LoF variants in NTHL1 do not confer any substantial risk for colorectal cancer and do not undergo bi-allelic inactivation." (PMID 33980861, 2021). "In addition, 16 patients were heterozygous for pathogenic variants in genes known to have a recessive pattern of inheritance, i.e., the colorectal cancer (CRC) predisposition genes MUTYH and NTHL1." (PMID 31263571, 2019). "Moreover, the recent advances in molecular techniques, in particular Next-Generation Sequencing, have led to the identification of many new genes involved in the predisposition to colorectal cancers, such as RPS20, POLE, POLD1, AXIN2, NTHL1, MSH3, RNF43 and GREM1." (PMID 36768460, 2023).
colorectal cancer (continued). "The cancer-predisposing syndrome caused by biallelic mutations in NTHL1 may not be a solely colorectal cancer (CRC) and polyposis syndrome but rather a multi-tumor recessive disease." (PMID 31227763, 2019). "Due to the ascertainment bias in the reported individuals, accurate cancer risk estimation, mostly for colorectal cancer, has not been possible to calculate; even though, available data suggest that the lifetime risk of CRC in the NTHL1 tumor syndrome is likely high." (PMID 33806975, 2021).